MGMT (O-6-methylguanine-DNA methyltransferase)
Diseases named in the same sentence as MGMT in open-access papers (continued):
Sharing a sentence is not in itself a finding about the gene and the disease.
tumor (continued). "Current practice measures MGMT from lysates or fixed cells generated from homogenized biopsied tumor tissue." (PMID 27035132, 2016). "Tumor regrowth led to a fifth resection, at which time MGMT was reported to be methylated, which was followed by concurrent radiotherapy and temozolomide." (PMID 27028405, 2016). "Multivariate analysis of OS and PFS included age, KPS, tumor grade, extent of resection, radiotherapy, TMZ chemotherapy, IDH1 mutation and MGMT promoter methylation." (PMID 27590514, 2016). "MLH1 and MGMT methylation correlated inversely when the tumor was located in the lower third of the stomach (coefficient, –0.48; p = 0.01)." (PMID 26810771, 2016). "Inhibiting MGMT with pseudosubstrates such as BG has been found to increase tumor sensitivity to alkylating agents." (PMID 27035132, 2016). "MGMT promoter methylation status was known for 51/59 patients: the MGMT promoter was methylated in 16/51 tumor samples (31%)." (PMID 26637806, 2016). "Increased chemotherapy resistance was observed in 3D culture tumor cells as a result of increased stemness and upregulation of cell self-rehabilitation protein, MGMT." (PMID 27486877, 2016). "The analyses of the correlation of MGMT methylation, gender, tumor types, and tumor stage used the random-effects model (all P < 0.1), but a fixed-effects model was used for H. pylori infection status and age status (P > 0.1)." (PMID 27824946, 2016). "By combining imaging biomarkers that describe different aspects of tumor appearance, we can build a more accurate model to predict MGMT methylation." (PMID 27277032, 2016). "The increasing of MGMT level correlates well with the enhancement of tumor resistance to these alkylating agents." (PMID 27347909, 2016). "In the multivariate model that included KPS, tumor localization, MGMT promoter status, surgical resection status, temozolomide therapy, Dmean IL SVZ ≥ 40 Gy, and Dmean CL SVZ ≥ 30 Gy, average CL SVZ dose higher than 30 Gy remained a prognostic factor for PFS." (PMID 27429623, 2016). "A nuclease-protected probe, NR-1, was prepared and tested in tumor cell lysates, demonstrating an ability to evaluate relative levels of MGMT repair activity in twenty minutes." (PMID 27035132, 2016). "The present study is one of the largest reports describing prolactinoma MGMT expression and its relationship with patient and tumor characteristics." (PMID 26400193, 2015). "Although several markers of tumor proliferation and metabolism have been identified in GBM and are used clinically (EGFRvIII amplification, MGMT promoter methylation, IDH1 mutation status), prognostic markers of invasive capacity are largely lacking." (PMID 25714433, 2015). "All of the tumors gave informative results; however, only one tumor, case 7, was found to have MGMT promoter methylation." (PMID 25823555, 2015). "Activity of O6-methylguanine DNA methyltransferase (MGMT) in the tumour cells in our patient was assessed as very low." (PMID 26221547, 2015). "Tumor-adjacent tissues showed higher methylation status of RASSF1A, HIN-1 and MGMT promoters than tumor-distant tissues, indicating field cancerization." (PMID 26370119, 2015). "In patients with tumor grade 3, the MGMT promoter was found to be more frequently methylated than in patients with tumor grade 2." (PMID 26370119, 2015). "Given that expression of MGMT is regulated by multiple molecular mechanisms we searched for cellular regulators of MGMT that can be specifically targeted to lower the levels of MGMT in tumour cells and re-sensitize these tumours to chemotherapeutic drugs." (PMID 26603103, 2015). "Tumor MGMT promoter and isocitrate dehydrogenase 1 (IDH1) status were determined to be methylated and wild-type, respectively." (PMID 26423602, 2015). "Matching criteria were, MGMT promotor methylation, recurrent surgery, eloquent location, tumor size and age." (PMID 26115409, 2015).
tumor (continued). "Three previously established and characterized patient tumor-derived MGMT unmethylated GSC cell lines, D431, S496 and E445 were used to study TMZ sensitivity." (PMID 26546412, 2015). "The expression of MGMT was repressed in celecoxib-treated xenografts as compared with control xenograft tumours." (PMID 26603103, 2015). "MGMT removes alkylating adducts from the O6 position of guanine and protects cells from cytotoxic and mutagenic effects, conferring a resistance of the tumor cells to alkylating agent chemotherapy including TMZ." (PMID 25955568, 2015). "Expression of MGMT was completely blocked in β-catenin-depleted xenografts as compared with control xenograft tumours." (PMID 26603103, 2015). "Of note, these authors demonstrated a sensitivity of ~50–80 % and a specificity of 100 % of methylated MGMT in serum and plasma compared to the result of MGMT analysis of the tumor tissue." (PMID 25720744, 2015). "A statistically significant difference between the methylation status in tumor and tumor-adjacent tissues was also found for MGMT, but only for the subgroup." (PMID 26370119, 2015). "The methylation status of the RASSF1A, HIN-1 and MGMT promoters was significantly lower in tumor-distant tissues than in tumors." (PMID 26370119, 2015). "We explored the relationship between ADAMTS14 and MGMT methylation in normal and tumor tissues of CRC patients and correlated these findings with tumor genotype and phenotype, including clinico-histological parameters." (PMID 25638164, 2015). "In case of RASSF1A, HIN-1 and MGMT promoters, tumor-adjacent tissues showed higher methylation status than tumor-distant tissues, the difference was, however, not statistically significant." (PMID 26370119, 2015). "As many chemotherapeutic agents, such as alkylating drugs, interact with DNA at this position to induce apoptosis, the increase in the expression of MGMT confers drug resistance phenotypes on the tumor cells." (PMID 29061940, 2015). "Samples were classified into MGMT-methylated or demethylated based on the values of three probes located within the MGMT 5′ CpG island and enhancer region that exhibits a bimodal distribution in tumor samples." (PMID 25638164, 2015). "O-6-methylguanine-DNA methyltransferase (MGMT), an enzyme regulated primarily through promoter methylation, repairs DNA damage caused by alkylating lesions and thus rescues tumor cells from apoptosis." (PMID 25889687, 2015). "Mechanistically, MGMT methylation reduces gene expression, which decreases tumor cells' ability to repair temozolomide-induced DNA damages, thus increasing drug sensitivity." (PMID 25762636, 2015). "A further alternative was to sensitive tumor cells to temozolomide by concomitant use of the pseudosubstrate O6-benzylguanine (O6-BG) which also depletes MGMT by activating its ‘suicidal’ dealkylation mechanism." (PMID 26035292, 2015). "In conclusion, our data supports the use of inhibitors of Wnt signalling and temozolomide in combination as a treatment option for cancer patients expressing high levels of MGMT in their tumour." (PMID 26603103, 2015). "The resistance of tumor cells to the biological effects of alkylating agents like TMZ is due to the DNA repair protein O6-methylguanine-DNA methyltransferase (MGMT)." (PMID 26535188, 2015). "In patients with tumor grade 2, the methylation status of MGMT in tumor-distant tissues was most frequently < LOD whereas in patients with tumor grade 3, the MGMT promoter was found to be methylated." (PMID 26370119, 2015). "This positive outcome is particularly interesting in view of the MGMT-positive status of these tumor cells, because it indicates that NEO212 can reach concentrations in vivo that are sufficiently high to exert therapeutic activity." (PMID 26282951, 2015). "O6-methylguanine-DNA methyltransferase (MGMT) is a DNA-repair protein that protects GBM tumor cells against alkylating agents by removing alkyl adducts from the O6-position of guanine." (PMID 25927334, 2015).
tumor (continued). "A similar distribution was achieved for MGMT promotor (methylated in 53%), recurrent surgery (19%) and categorical distribution of eloquent location (eloquent in 45%) and tumor size (>40cc in 39% of cases)." (PMID 26115409, 2015). "Treatment with 5-Aza, which can demethylate the MGMT promoter, increased MGMT expression in tumor cell lines." (PMID 26447477, 2015). "In mouse xenograft models of human GBM, the level of human MGMT mRNA in serum exosomes was elevated in mice bearing MGMT-positive tumour (GBM10)." (PMID 25959588, 2015). "In this study, the authors propose the inhibition of the Wnt signalling pathway as an alternative strategy to modulate MGMT expression and sensitize tumours to chemotherapy." (PMID 26603103, 2015). "Most of the tumors showed homogenous methylation of DAPK1 and MGMT, in some tumor tissues the promoter of these genes was methylated heterogeneously." (PMID 26370119, 2015). "Pathological examinations for this tumor revealed a PTEN-mutated, MGMT-methylated, and VEGF-amplificated condition." (PMID 25889578, 2015). "The inserted shRNA can target the DNA repair protein, MGMT, in tumor cells and multiply by several 100- to several 1,000-fold in parallel with viral replication." (PMID 25295108, 2014). "Treatment started at day 6, when tumor volume reached 60 mm3, with intratumoral (Intralesional - IL) injection of 25 ug of MGMT-kB1-LODN." (PMID 25460932, 2014). "Imidazotetrazine analogues of TMZ and the BH3 mimetic obatoclax are promising clinical candidates in drug resistant MB tumours expressing MGMT and BCL2 anti-apoptotic members respectively." (PMID 24887326, 2014). "The GO6 methyl adduct can, however, be repaired by O6-methylguanine-DNA methyltransferase (MGMT), resulting in active resistance to TMZ in tumours in which MGMT is proficient." (PMID 25014631, 2014). "Immunohistochemistry revealed intense nuclear staining and weak cytoplasmic staining for MGMT in the tumor cells." (PMID 24932232, 2014). "When conveying shRNA, oncolytic viruses are expected to effect a marked reduction in the tumor MGMT level, which should result in an increase in the cytotoxicity of TMZ." (PMID 25295108, 2014). "With tumour cells high in MGMT levels, pre-treatment with inactivators such as O-benzylguanine has been shown to enhance the in vitro and in vivo activity of TMZ." (PMID 25014631, 2014). "MGMT status was assessable in 19 patients (73%), 14 on primary tumor tissue and 5 in the recurrent tumor tissue; MGMT resulted methylated in 10 (53%) cases and unmethylated in 9 (35%) cases." (PMID 24877084, 2014). "Tumor MGMT methylation status was also shown to have a prognostic value for progression-free survival of anaplastic glioma patients treated with radiotherapy alone." (PMID 25229548, 2014). "Excluding the slow proliferating #23 GSC line, the anti-tumor effects of TMZ in MMR-proficient cell lines inversely correlated with MGMT activity/expression at a statistically significant level." (PMID 24593254, 2014). "As expected, treatment with 100 mg/kg TMZ was ineffective while treatment with MGMT-kB1-LODN either as a monotherapy or in combination with TMZ significantly inhibited tumor growth (p<0.05)." (PMID 25460932, 2014). "Clinical data including age, Karnofsky performance score, preoperative tumor volume and location, extend of resection, MGMT promoter methylation status, time to progression (PFS), overall survival (OS) and adjuvant therapies were reviewed for every patient." (PMID 24135848, 2014). "Five patients were shown to harbor a methylated and four patients to harbor an unmethylated MGMT promoter in their tumor tissue." (PMID 24359605, 2014).
tumor (continued). "Pyrosequencing after prior DNA bisulfite modification has emerged as a reliable, accurate, fast and easy-to-use method for MGMT promoter methylation testing in tumor tissues (including formalin-fixed and paraffin-embedded samples)." (PMID 24359605, 2014). "60% of GBM tumours have unmethylated MGMT promoter regions, resulting in an overexpression of the DNA repair protein O6-methylguanine-DNA methyltransferase (MGMT), which is responsible for tumour resistance to TMZ chemotherapy." (PMID 24909675, 2014). "The cytotoxic effect of TMZ chemotherapy is therefore influenced by the ability of tumour cells to re-synthesise MGMT and maintain steady state levels of the protein." (PMID 24909675, 2014). "When coupled with mTOR inhibition, not only would there be a decrease in MGMT levels, but the tumour cell would be compromised in its ability to synthesise new protein, thus sensitising the cells to further TMZ treatment." (PMID 24909675, 2014). "In this case the sole analysis of MGMT promoter methylation status would have led to underestimation of tumor chemosensitivity." (PMID 24593254, 2014). "84% of grade III tumours and 17% of grade IV had IDH1 or IDH2 mutations that conferred a better prognosis in both; MGMT methylation (defined as average value across 16 CpGs ≥ 10%) occurred in 75% of tumours and was also associated with improved survival." (PMID 24952577, 2014). "Quality assurance should also include histopathological verification of sufficient tumor content in the sample submitted for MGMT promoter methylation testing." (PMID 24359605, 2014). "A tumor low in MGMT will respond well to initial TMZ therapy but at the cost of accumulated mutations." (PMID 24287492, 2013). "Higher number of cases with methylated MGMT gene were tumor stage 3 (52%) and moderately differentiated grade (66%)." (PMID 23573237, 2013). "Generally, tumour mass cells are stationary due to increased cell-cell adhesion, chemosensitive due to lower expression of MGMT, and less capable of tumour formation due to their lower stemness." (PMID 23818228, 2013). "Our aim was to develop a new protocol for MGMT immunohistochemistry with good agreement between observers and good correlation with molecular genetic tests of tumour methylation." (PMID 24252243, 2013). "Efficient in vivo transduction of the shMGMT vector into GBM xenografts decreased MGMT expression and inhibited tumor growth following TMZ treatment." (PMID 24287492, 2013). "Tumor cell populations with chromosome 10 monosomy (1∶1) or MGMT locus deletion (1∶2) were detected in 32 (53.3%) and 9 (15%) patients, respectively." (PMID 23505468, 2013). "Several represented genes, TIMP3, p16 (CDKN2A), p14, MGMT, CDH1, RASSF1A and DAPK, are highly sensitive to methylation-induced repression in HNSCC tumor and saliva samples, and are directly associated with tumor development." (PMID 25587491, 2013). "Therapy with alkylating agents like TMZ is worthwhile in a subpopulation of patients showing methylation of the MGMT gene in their tumor; however patients with unfavorable MGMT status are resistant towards therapy with TMZ." (PMID 23704990, 2013). "Further, we observed that expression of MGMT, a major chemoresistance enzyme, increased towards the tumour edges in control tumours, and that ZEB1 and MGMT co-localise." (PMID 23818228, 2013). "The methylation status of the MGMT promoter was consistent between original tumor and cell line pairs." (PMID 23951083, 2013). "Methylated MGMT gene was observed in 47% (29/62) cases of CRC in the tumor region and in 13% cases in the adjacent control regions." (PMID 23573237, 2013). "It is the first in vitro study to investigate possible synergy between these three agents, and to assess the influence of MGMT promoter methylation status on tumour response." (PMID 23510353, 2013).
tumor (continued). "MGMT is a repair protein that specifically removes promutagenic alkyl groups from the O6 position of guanine in DNA, thereby protecting tumor cells against alkylating agents." (PMID 23977117, 2013). "Quantitation of MGMT expression in tumour cells in double-labelled images will require special thresholding protocols but should provide useful comparison with the methylation ratios obtained from MLPA." (PMID 24252243, 2013). "Tumor stage, metastasis and lymphatic invasion were found to be significantly correlated with the presence of methylated MGMT gene (p-values 0.018, 0.044 and 0.048, respectively)." (PMID 23573237, 2013). "Stratification of clinical treatment response by MGMT-methylation status demonstrates poorer outcomes for patients with MGMT-unmethylated tumours." (PMID 23510353, 2013). "In a tumor with a hypermethylated MGMT promoter, MGMT expression is reduced and cytotoxicity of alkylating agents is enhanced." (PMID 24160898, 2013). "Our aim was to produce a visual separation of tumour cells and non-tumour cell elements on the same histological slide and thereby greatly simplify the assessment of MGMT immunostaining in tumour cell nuclei." (PMID 24252243, 2013). "MGMT was expressed independently of ZEB1 in these tumours, supporting c-MYB as intermediate regulator of MGMT." (PMID 23818228, 2013). "We have used such a platform to develop a novel technique, namely double-labelling immunostaining of MGMT and a "cocktail" of non-tumour antigens (CD34, CD45 and CD68)." (PMID 24252243, 2013). "The proposed MGMT-STP27 prediction model allows mining of datasets derived on the HM-450K or HM-27K BeadChip to explore effects of distinct epigenetic context of MGMT methylation suspected to modulate treatment resistance in different tumor types." (PMID 22810491, 2012). "One of the main mechanisms of tumor resistance to TMZ is thought to be mediated by O6-methylguanine-DNA methyltransferase (MGMT)." (PMID 22396071, 2012). "Since patients with MGMT overexpression in tumors respond more poorly to alkylating agents, co-administration of O6-BG to deplete the tumor pools of MGMT to enhance drug cytotoxicity has been previously attempted in a clinical setting." (PMID 22530127, 2012). "We found that the MGMT promoter was methylated in 13 out of the 23 (57%) analyzed primary tumor samples and in the examined cell line." (PMID 22246327, 2012). "We found that the MGMT promoter in 57% of the analyzed primary tumor samples and in the cell line was hypermethylated." (PMID 22246327, 2012). "An MGMT promoter methylation analysis was performed on tumor tissues sampled from the initial neuro-surgery before radiotherapy and TMZ." (PMID 24213227, 2012). "The MGMT TSG was found in 13 out of the 23 (57%) analyzed primary tumor samples as well as in the examined cell line methylated." (PMID 22246327, 2012). "MGMT promoter methylation analysis was performed on tumor tissue taken from the initial neurosurgery process." (PMID 24213227, 2012). "Prognosis is highly variable depending on histopathology, grade, patient age, and genetic tumor factors such as the presence of a 1p/19q co-deletion, IDH1 and IDH2 mutations, and MGMT promoter methylation." (PMID 22390413, 2012). "MGMT expression statistically significantly (p<0.01) decreased in the tumor samples with a hypermethylated MGMT promoter region." (PMID 22246327, 2012). "The distribution of MGMT promoter hypermethylation shows that it starts to develop at an early stage of GL and the gene inactivation is stable even on tumour progression." (PMID 22264301, 2012). "MGMT promoter methylation can also help to distinguish true tumor progression from pseudoprogression." (PMID 23346075, 2012). "MGMT gene silencing was assumed if MGMT promoter methylation was present and the fraction of tumor cells expressing MGMT was 20% or less." (PMID 23110891, 2012).